A1BG-AS1 (A1BG antisense RNA 1)
Synonyms: FLJ23569; A1BG-AS; A1BGAS; NCRNA00181
Gene: Long non-coding RNA gene on chromosome 19 (58,347,718 to 58,355,455, forward strand). Ensembl gene ENSG00000268895.
Diseases named in the same sentence as A1BG-AS1 in open-access papers:
A1BG-AS1 is named in the same sentence as 2 diseases in open-access papers, as found by Europe PMC text mining. Sharing a sentence is not in itself a finding about the gene and the disease. The quoted sentences say what the papers report.
breast carcinoma (1 paper, 2023). "Similarly, A1BG-AS1 is overexpressed in different cancers, including hepatocellular and breast carcinoma." (PMID 36400229, 2023).
A1BG-AS1 also shares sentences with these, for which no sentence is quoted: cancer (1 paper).